CXCR5 (C-X-C motif chemokine receptor 5)
Diseases named in the same sentence as CXCR5 in open-access papers (continued):
Sharing a sentence is not in itself a finding about the gene and the disease.
MALT lymphoma (3 papers, 2022 to 2025). An indolent, extranodal type of non-Hodgkin lymphoma composed of small B-lymphocytes (centrocyte-like cells). "Furthermore, CXCR3, CXCR4, and CXCR5 have been implicated in the pathogenesis of MALT lymphoma." (PMID 39451532, 2024). "Immunofluorescence double staining showed the co-expression of CXCL13 and CXCR5 in MALT lymphoma samples." (PMID 40078987, 2025). "Consequently, targeting the CXCL13/CXCR5 signaling axis represents a promising immunotherapeutic approach for managing and treating ocular adnexal MALT lymphoma." (PMID 40078987, 2025). "In MALT lymphoma cells, the B-cell attracting chemokine 1 (BCA-1) and its receptor C-X-C motif chemokine receptor 5 (CXCR5) are augmented, which regulate B-cells and promote the production of the inflammation-causing interleukin-8 (IL-8)." (PMID 35480118, 2022).
membranous nephropathy (3 papers, 2017 to 2023). "More recent study on HBV-associated membranous nephropathy revealed that the percentage of CD4+CXCR5+ follicular T helper (Tfh) cells was negatively correlated with the value of eGFR." (PMID 28274240, 2017). "Significantly higher frequency of CD4+/CXCR5+, CD4+/CXCR5+/ICOS+ and CD4+/CXCR5+/PD-1+ TFH cells, and higher serum levels of IL-17A, IFN-γ, IL-2, IL-10, IL-4 and IL-21 were detected in hepatitis B virus-associated membranous nephropathy patients compared to the healthy controls." (PMID 28770269, 2018).
nasopharyngeal carcinoma (3 papers, 2022 to 2025). A carcinoma arising from the nasopharyngeal epithelium. "However, in EBV‐associated nasopharyngeal carcinoma (NPC), the presence of PD‐1+ CXCR5− CD4+ Th‐CXCL13 cells within TLS may be associated with improved prognosis." (PMID 40591148, 2025).
nephritis (3 papers, 2019 to 2025). Inflammation of renal tissue. "For immunofluorescence assay, we observed that CD4+CXCR5+ T cells were significantly recruited at the site of nephritis of LN mice." (PMID 41164191, 2025). "And in MRL/lpr mice, CXCL13 was involved in the development of nephritis by promoting the recruitment of CXCR5+ T cells to the kidney." (PMID 41164191, 2025). "In this study, CD4+ CXCR5+ and CD4+ CXCR5+ ICOS+ Tfh cells were abnormally elevated in children with non-nephritis-type HSP, and were significantly associated with PGA-IgA, especially CD4+ CXCR5+ ICOS+-activated Tfh cells." (PMID 34250253, 2021). "Recent studies found a predominant expansion of CD11c+T-bet+ B cell lacking surface IgD, CD27 and CXCR5 expression in PBMCs of African-American SLE patients with elevated serum anti-Smith and anti-RNA autoantibodies levels and nephritis development." (PMID 31795353, 2019).
Obesity (3 papers, 2023 to 2025). Accumulation of substantial excess body fat. "In similarity to the Tfh, the Tfc also display higher expression of CXCR5 in OB (p < 0.05), particularly in Class II obesity, as well as a higher percentage of activated Tfc cells (OB: 10% ± 5.3 vs. nOB: 6.6% ± 4.0, p < 0.05)." (PMID 38397455, 2024). "To further interrogate how functional differentiation pathways are affected by obesity and bariatric surgery, we next assessed CXCR5+CD11c-IgD-CD27- DN1 and CD11c+CXCR5-IgD-CD27- DN2 B cell subset as well as CD27+CD38++ plasmablast frequencies." (PMID 37463992, 2023).
pemphigus (3 papers, 2016 to 2022). Pemphigus is a group of rare autoimmune diseases that cause blistering of the skin and mucous membranes (mouth, nose, throat, eyes, and genitals).This conditioncan occur at any age, but often strikes people in middle or older age. "Most likely, these cells represent a population of IL-21-positive Tfh cells although in our pemphigus cohort the median percentage of IL-21 single positive T cells is lower compared to the median frequency of CD4+CXCR5+ T cells (16.91% CD4+ T cells)." (PMID 26872212, 2016). "Notably, CCL19, CCL26, CCL27 and CXCR5 were highly expressed chemokines and chemokine receptors detected in pemphigus group." (PMID 35449056, 2022). "Circulating (c)Tfh cells (defined as CD4+CXCR5+ T cells) and Th17 cells (IL-17-producing CD4+ T cells) were significantly increased in pemphigus along with increasing IL-21 plasma concentrations suggesting an enhanced activation of IL-21-producing T cells in pemphigus." (PMID 26872212, 2016). "CXCR5 expression was higher in CD19hi B cells from the periphery of SLE and pemphigus patients but not from tonsil." (PMID 29066741, 2017).
pneumonia (3 papers, 2019 to 2025). An acute, acute and chronic, or chronic inflammation focally or diffusely affecting the lung parenchyma, caused by an infection in one or both of the lungs (by bacteria, viruses, fungi, or mycoplasma.). "Here, we characterized circulating CXCR5-expressing CD8+ T-cells in pneumonia individuals and analyzed their association with PCT level." (PMID 30866951, 2019). "The circulating CXCR5-expressing CD8+ T-cell has diagnostic value for current pneumonia severity, and could act as a biomarker for identifying a bacteria-associated exacerbation." (PMID 30866951, 2019). "In this study, we aimed to determine if CXCR5 + CD8+ T cell was a valuable biomarker for bacterial infection in subjects with pneumonia." (PMID 30866951, 2019).
primary immunodeficiency (3 papers, 2015 to 2022). "However, patients with primary immunodeficiency in ICOS have reduced numbers of circulating CXCR5+ CD4+ T cells." (PMID 26333070, 2015).
Prostate Tumor (3 papers, 2013 to 2025). "We have previously shown that PCa cell lines and prostate tumors express CXCR5 and respond to CXCL13 that is significantly elevated in the serum of PCa patients compared to serum of patients." (PMID 31628349, 2019). "Furthermore, we established a role for CXCL13 and CXCR5 interaction in prostate tumor progression and elucidated some of the molecular and cellular processes mediated by activation of this chemokine receptor." (PMID 23773523, 2013).
psoriasis (3 papers, 2016 to 2024). An autoimmune condition characterized by red, well-delineated plaques with silvery scales that are usually on the extensor surfaces and scalp. "Double-staining immunofluorescence further identified the higher infiltration of CXCR5+CD4+ T cells in lesions of psoriasis patients." (PMID 27774460, 2016). "Then, the expression of top 5 potential candidate genes (PBX1, CYB5R4, SAR1A, CXCR5, MFSD6) of miR-3074-5p was detected in normal and psoriasis tissues by qPCR; our result revealed that PBX1 was the most upregulated genes in psoriasis tissues compare to normal ones." (PMID 38240925, 2024).
pulmonary TB (3 papers, 2014 to 2023). "According to the data obtained, the level of peripheral blood CXCR5-expressing Tfh cells in patients with active pulmonary tuberculosis is significantly lower than that in LTBI patients." (PMID 37626620, 2023). "Recently, decreased frequencies of CD4+CXCR5+ T helper cells were reported in the blood of active pulmonary TB patients when compared with the blood of latent TB patients." (PMID 26785168, 2016). "To determine the distribution of circulating Tfh cells in human TB, we measured the frequencies of Tfh cells exvivo and following TB - antigen or polyclonal stimulation in pulmonary TB (PTB; n = 30) and latent TB (LTB; n = 20) individuals, using the markers CXCR5, PD-1 and ICOS." (PMID 25343703, 2014).
retinal degeneration (3 papers, 2019 to 2020). Degeneration of the retina. "Recently, we demonstrated that aged CXCR5 knockout mice (CXCR5−/−, KO) develop retinal degeneration (RD)." (PMID 32492870, 2020). "Previous research has shown that CXCR5−/− mice develop retinal degeneration (RD) with age, a characteristic related to age macular degeneration (AMD)." (PMID 31474986, 2019). "CXCR5−/− mice may also develop retinal degeneration with pathophysiological changes, such as activation of microglia and accumulation of inflammatory cells, loss of ZO-1 indicative of impaired blood-retinal barrier function after ischemia-reperfusion injury." (PMID 33161894, 2020).
schizophrenia (3 papers, 2016 to 2024). A major psychotic disorder characterized by abnormalities in the perception or expression of reality. "A study of 18 patients with schizophrenia (17 treated with clozapine) vs. 18 healthy persons found elevated monocytes, NK cells, naïve B cells and CXCR5+ memory CD4 cells in the schizophrenia group, and decreased number of DC and several T cells populations." (PMID 30766494, 2018). "Schizophrenia cases had increased relative numbers of NK cells, naïve B cells, CXCR5+ memory T cells and classical monocytes; and decreased numbers of dendritic cells (DC), HLA-DR+ regulatory T-cells (Tregs), and CD4+ memory T cells." (PMID 27244229, 2016). "In schizophrenia, increased numbers of natural killer (NK) cells, naive B cells, CXCR5 memory cells, and classical monocytes have been demonstrated and decreased numbers of dendritic cells (DCs), HLA-DR+ regulatory T cells (Treg), and CD4+ memory cells have been demonstrated." (PMID 39596417, 2024).
serous ovarian cancer (3 papers, 2022 to 2025). "The combined assessment of CXCL13, CXCR5, and CD8+ T cells serve as an independent predictor of survival in high-grade serous ovarian cancer." (PMID 40352278, 2025). "In high-grade serous ovarian cancer, elevated CXCL13 expression correlates with increased infiltration and activation of CXCR5+ CD8+ T cells within the TME." (PMID 40352278, 2025). "A large study of high-grade serous ovarian cancer found CXCL13 enhanced immune efficacy in combination with PDL1 by promoting the expansion and activation of CXCR5 + CD8 + T cells." (PMID 36704336, 2022).
squamous cell carcinoma (3 papers, 2013 to 2022). A carcinoma arising from squamous epithelial cells. "Based on these findings, we investigated the expression of CXCR5 and CXCL13 in patient samples of NSCLCs, evaluating the expression of CXCR5 in normal, squamous cell carcinoma (SCC), and adenocarcinoma (AC) tissues by immunohistochemical staining." (PMID 25271023, 2014). "Consistent CXCR5 upregulation is also observed in squamous cell carcinomas, suggesting that CXCR5/CXCL13 interactions may serve as a novel complementary pathway mediating metastasis to the lymph nodes." (PMID 24259307, 2013). "Lung biopsies from patients with non-neoplastic cells (n=8), squamous cell carcinoma (SCC; n=24), or adenocarcinoma (AC; n=54) were stained for CXCR5." (PMID 25271023, 2014).
systemic sclerosis (3 papers, 2020 to 2025). A chronic disorder, possibly autoimmune, marked by excessive production of collagen which results in hardening and thickening of body tissues. "Further, the levels of CXCR5+ICOS+PD-1+ Tfh cells are strongly associated with dermal fibrosis in patients with systemic sclerosis (SSc)." (PMID 32676074, 2020). "In addition, CXCR5+ICOS+PD-1+Tfh levels were associated with systemic sclerosis (SSc)." (PMID 40433386, 2025). "Furthermore, systemic sclerosis patients’ dermal fibrosis is closely correlated with the presence of CXCR5 + ICOS + PD-1 + Tfh cells (SSc)." (PMID 36835428, 2023).
T-cell lymphoma (3 papers, 2021 to 2024). "We envision that CXCR5 CAR-T cell therapy may also be suitable for the treatment of CXCR5+ T-cell lymphoma entities because of the developmental relationship between Tfh cells and these T cell malignancies, both sharing CXCR5 as a potential target." (PMID 33431832, 2021).
tetanus (3 papers, 2014 to 2021). A serious infectious disorder that follows wound contamination by the Gram-positive bacterium Clostridium tetani. "Furthermore, characterization of tetanus-specific CD4 T cells in healthy human donors (identified using HLA tetramers bearing tetanus peptide), demonstrated the existence of this CXCR5+CXCR3−PD-1low phenotype among resting antigen-specific memory cells." (PMID 25699040, 2015). "One report described that tetanus-antigen-specific proliferation was induced in CD4+CD45RO+CXCR5−but not CD4+CD45RO+CXCR5+ cells, thus suggesting that Tfh cells likely disappear along with germinal centers, and are prone to apoptosis due to their high levels of Fas expression." (PMID 25699040, 2015).
ulcerative colitis (3 papers, 2017 to 2024). An inflammatory bowel disease involving the mucosal surface of the large intestine and rectum. "CXCR5 and CXCL13 expression were also readily detected in gut associated lymphoid tissue (GALT) and lymphoid aggregates in gut samples of ulcerative colitis patients." (PMID 28827539, 2017).
acute lymphoblastic leukemia (2 papers, 2020 to 2021). Leukemia with an acute onset, characterized by the presence of lymphoblasts in the bone marrow and the peripheral blood. "The malignant B cells from CLL or acute lymphocytic leukemia (ALL) patients take advantage of the CXCR5/CXCL13 axis and the CCR7/CCL19 axis for resistance to TNFα-induced apoptosis via upregulation of paternally expressed gene 10 (PEG10) and subsequent stabilization of caspase-3 and caspase-8." (PMID 34947813, 2021).
acute myeloid leukemia (2 papers, 2022 to 2023). Acute myeloid leukemia (AML) is a group of neoplasms arising from precursor cells committed to the myeloid cell-line differentiation. "Our analysis data suggested the predictive potential of CXCR as four CXCR members (CXCR3, CXCR4, CXCR5, and CXCR6) were significantly related to better clinical outcomes in HNSCC, as reported in acute myeloid leukemia." (PMID 35978426, 2022).
adenoma (2 papers, 2024). A neoplasm arising from the epithelium. "We further analyzed the T follicular helper (Tfh) response, and CD4+PD1+CXCR5+ cells were significantly decreased in adenoma grade II (3.95 vs. 0.63, P = 0.0157), grade III (3.95 vs. 0.26, P = 0.0002), and CRC (3.95 vs. 0.16, P < 0.0001) compared with the control." (PMID 38343544, 2024). "In addition, there are two other significantly downregulated receptor genes, CXCR5 and CCR2, which both show a marked downregulation in adenoma samples." (PMID 39409185, 2024). "Moreover, the percentage of CD4+PD1+CXCR5+ cells decreased from adenoma grade I to III and even in CRC, primarily attributed to the change in programmed cell death protein 1 (PD1) but not CXCR5." (PMID 38343544, 2024).
amyotrophic lateral sclerosis (2 papers, 2023 to 2024). Amyotrophic lateral sclerosis (ALS) is a neurodegenerative disease characterized by progressive muscular paralysis reflecting degeneration of motor neurons in the primary motor cortex, corticospinal tracts, brainstem and spinal cord. "In a mouse model of amyotrophic lateral sclerosis, CXCL13/CXCR5 signalling was strongly up-regulated among motor neurons, but silencing the axis resulted in increased motor neuron loss." (PMID 37765263, 2023).
angioimmunoblastic T-cell lymphoma (2 papers, 2021 to 2023). A mature T-cell non-Hodgkin lymphoma, characterized by systemic disease and a polymorphous infiltrate involving lymph nodes and extranodal sites. "Previously, we have shown that neoplastic T cells of angioimmunoblastic T-cell lymphoma (now TFHL-AI) express CXCR5." (PMID 38203606, 2023). "In this study, we performed a comprehensive TFH phenotyping in PTCLs with an extended 7-TFH marker panel by adding CXCR5 and CD134, which we had previously proven to be consistently expressed in the neoplastic T cells of TFHL-AI (formerly angioimmunoblastic T-cell lymphoma)." (PMID 38203606, 2023).
antibody deficiency (2 papers, 2016 to 2022). "In conclusion, impaired TCR-mediated activation of CXCR5-negative CD4+ memory T cells following stimulation with vaccine antigen or superantigen identifies patients with primary antibody deficiency and impaired IgG responses after BNT162b2 vaccination." (PMID 35237272, 2022).
Anxiety (2 papers, 2014 to 2020). Intense feelings of nervousness, tension, or panic often arise in response to interpersonal stresses. "Previous studies showed that CXCR5−/− mice have more immature neurons in the dentate gyrus, an increase in baseline locomotor activity, and decreased anxiety-like behavior." (PMID 33161894, 2020).
Cirrhosis (2 papers, 2015 to 2021). A chronic disorder of the liver in which liver tissue becomes scarred and is partially replaced by regenerative nodules and fibrotic tissue resulting in loss of liver function. "To examine B cell phenotypes in D-LC caused by HBV, we performed flow cytometry using a panel of 11 markers (CD19, CD10, CD38, IgD, CD21, CD27, CCR7, CXCR3, CXCR4, CXCR5, and IL-21R) and demonstrated the changes of B cell subsets for the first time in HBV-associated advanced cirrhosis." (PMID 34248941, 2021). "The frequencies of ICOS+ and CCR7+ CXCR5+CD45RA−CD4+ T cells were higher in HCC patients than in HC (P = 0.002 and P < 0.001, respectively), and the percentage of ICOS+ Tfh cells was correlated with the incidence of cirrhosis in HCC patients (P = 0.039)." (PMID 26517519, 2015).
dementia (2 papers, 2014 to 2023). Loss of intellectual abilities interfering with an individual's social and occupational functions. "CXCL13 is a B-lymphocyte chemotaxis factor and contributes to an inflammatory response by activating astrocytes via CXCR5 in a neuralgia model, but there are no reports of AD-type dementia." (PMID 37978479, 2023).
diabetic neuropathy (2 papers, 2020 to 2025). A chronic, pathological complication associated with diabetes mellitus, where nerve damages are incurred due to diabetic microvascular injury involving small blood vessels that supply these nerves, resulting in peripheral and/or autonomic nerve dysfunction. "For example, chemokine CXCL13 (C-X-C motif chemokine ligand 13) and its receptor CXCR5 (C-X-C chemokine receptor type 5) associated with inflammatory response have been demonstrated directly to be a pivotal regulator in the pathogenesis of painful diabetic neuropathy via ERK pathway." (PMID 32523943, 2020).
glioma (2 papers, 2022 to 2023). A benign or malignant brain and spinal cord tumor that arises from glial cells (astrocytes, oligodendrocytes, ependymal cells). "In this study, the results indicated that the mRNA expression of CXCR5 in glioma was higher than that in normal samples." (PMID 35571062, 2022). "Among them, one gene (CXCR5) was downregulated while five other genes (CXCR1, CXCR2, CXCR3, CXCR4, and ACKR3) were enriched in glioma compared with normal brain tissues." (PMID 35571062, 2022). "However, CXCR5 was not correlated to the prognosis of glioma." (PMID 35571062, 2022).
glomerulonephritis (2 papers, 2018 to 2025). A renal disorder characterized by damage in the glomeruli. "It was also observed that the frequency of PD-1+/CXCR5+ follicular helper T (TFH) cells was significantly increased in BXD2 mice, which spontaneously develop autoantibodies and subsequent glomerulonephritis, offering a useful animal model to study autoimmune lupus, compared with wild-type mice." (PMID 28770269, 2018).
Graves disease (2 papers, 2021 to 2024). Graves' disease is an autoimmune disorder that leads to overactivity of the thyroid gland (hyperthyroidism).It is caused by an abnormal immune system response that causes the thyroid gland to produce too much thyroid hormones. "Our study is aimed at detecting the expression of SLAM and SAP in patients with Graves' disease (GD) and analyzing the effect of SLAM/SAP on circulating blood CD4+CXCR5+Foxp3+ follicular regulatory T (Tfr) cells." (PMID 33987447, 2021).
Hepatitis (2 papers, 2021 to 2022). Inflammation of the liver. "Subsequently, we employed CXCR5-deficient mice to assess whether the role of FMT in controlling hepatitis progression was achieved by regulating TFR/TFH cell balance and found that FMT was able to improve liver inflammation in CXCR5-deficient EAH mice but later than EAH mice." (PMID 34912328, 2021). "Over-activated CXCR5+CD4+ T cells could help B cells to secret autoantibodies and accelerate liver inflammation." (PMID 35223685, 2022). "To explore whether the role of FMT in controlling hepatitis progression was achieved by regulating TFR/TFH cell balance, we employed CXCR5-deficient mice, which failed to develop discrete primary follicles." (PMID 34912328, 2021).